IGF2BP2 (insulin like growth factor 2 mRNA binding protein 2)
Diseases named in the same sentence as IGF2BP2 in open-access papers (continued):
Sharing a sentence is not in itself a finding about the gene and the disease.
glioma (34 papers, 2019 to 2025). A benign or malignant brain and spinal cord tumor that arises from glial cells (astrocytes, oligodendrocytes, ependymal cells). "The protein complex formed between HOXD-AS2 and IGF2BP2 is associated with poorer prognosis in glioma, with STAT3 playing a role in this feedback loop." (PMID 38474421, 2024). "Further investigation into the molecular mechanisms underlying the role of IGF2BP2 in glioma is warranted." (PMID 38682020, 2024). "A similar risk signature (ALKBH5, IGF2BP2, IGF2BP3, HNRNPA2B1, YTHDF1, YTHDF2, RBM15, and WTAP) was shown to be prognostic for glioma patients, and the expression of IGF2BP2 and IGF2BP3 was linked to tumour occurrence, development, and progression." (PMID 36831575, 2023). "Meanwhile, SUMOylation of IGF2BP2 inhibited by site mutation significantly inhibited cell proliferation, migration, invasion and VM ability of glioma cells." (PMID 34345216, 2021). "IGF2BP2 expression also associates with etoposide resistance in glioma cells." (PMID 38072944, 2023). "However, the mechanism underlying the role of IGF2BP2 in glioma resistance remains elusive, and its association with lncRNAs thus merits further attention." (PMID 35141227, 2021). "Through regulating the OIP5–AS1/miR‐495‐3p axis, SUMOylation of IGF2BP2 increases angiogenesis simulation of glioma." (PMID 40919129, 2025). "In glioma tissues and cells, SUMOization of IGF2BP2 promotes HIF1α expression, which in turn leads to cancer cell invasion and angiogenesis." (PMID 40469197, 2025). "Within this cascade of pathways, the PI3K-AKT pathway can also be activated by elevated IGF2BP2 in gliomas, thereby promoting GBM cell proliferation, migration, invasion, and EMT." (PMID 40469294, 2025). "In glioma tissues and cells, there was an upregulation of IGF2BP2 and OIP5–AS1, and a downregulation of miR‐495‐3p." (PMID 40919129, 2025). "The mechanism of how IGF2BP2 affects autophagy in glioma cells are intriguing and require further investigation." (PMID 38682020, 2024). "This comprehensive exploration unveils the role of IGF2BP2 in glioma progression, shedding light on autophagy modulation and chemosensitization strategies for glioma therapy." (PMID 38682020, 2024). "Our findings not only contribute to understanding the intricate relationship between IGF2BP2, autophagy, and glioma progression but also hold potential biological significance." (PMID 38682020, 2024). "The fine‐tuned control exerted by IGF2BP2 on autophagy adds an extra layer of complexity to our understanding of glioma pathophysiology." (PMID 38682020, 2024). "IGF2BP2’s involvement in glioma includes interactions with various RNA elements and transcription factors." (PMID 38474421, 2024). "The TMA analysis provides clinical relevance to our observations, suggesting that the IGF2BP2‐p62 axis play a role in glioma pathogenesis." (PMID 38682020, 2024). "This study provides evidence for the significant role of IGF2BP2 in the regulation of cell viability, cell cycle progression, and colony‐formation in glioma cells, which suggests that IGF2BP2 plays a pivotal role in supporting cell survival and growth." (PMID 38682020, 2024). "As we continue to unravel the mechanisms by which IGF2BP2 influences autophagy, the potential for developing targeted therapies in glioma treatment becomes increasingly promising." (PMID 38682020, 2024). "This study provides insights into the role of insulin‐like growth factor 2 messenger RNA‐binding protein 2 (IGF2BP2) in glioma progression and its therapeutic potential." (PMID 38682020, 2024). "Nevertheless, the precise mechanism governing the impact of IGF2BP2 on glioma progression remains elusive." (PMID 38682020, 2024). "The emerging role of IGF2BP2 in glioma biology from several studies raises questions about its potential contribution and mechanism to glioma development and progression." (PMID 38682020, 2024).
glioma (continued). "Exploration of IGF2BP2 expression within glioma was conducted through a comprehensive analysis using the TCGA program database." (PMID 38682020, 2024). "IGF2BP2 plays a critical role in glioma progression, and knockdown of IGF2BP2 leads to cell autophagy, TMZ resensitization, and tumor suppression, making it a potential novel therapeutic target for glioma." (PMID 38682020, 2024). "This modification upregulates IGF2BP2 in glioma, fostering VM (vasculogenic mimicry) formation by stabilizing OIP5‐AS1 and disrupting miR‐495‐3p's inhibition of HIF‐1α and MMP14, critical VM components." (PMID 39377984, 2024). "To investigate the functional role of IGF2BP2 in glioma, we employed shRNA to knockdown IGF2BP2 expression in glioma cells, including HS683, U87, and U251." (PMID 38682020, 2024). "The correlation between IGF2BP2 and p62 expression levels in tumor samples of patients with glioma further extends our in vitro findings." (PMID 38682020, 2024). "This relationship persisted when examining survival outcomes distinctly within grade 2 and grade 3 gliomas, where higher expression of IGF2BP2 predicated shorter survival times." (PMID 38682020, 2024). "Our study underscores the intricate relationship between IGF2BP2, autophagy, and glioma progression." (PMID 38682020, 2024). "The results presented in this study suggest that IGF2BP2 plays a role in glioma cell survival and autophagy regulation." (PMID 38682020, 2024). "Compared with NHAs, COL22A1, and IGF2BP2 mRNA levels were significantly increased in the glioma cell lines, while MPO levels were instead similar." (PMID 37737709, 2023). "Accumulating evidence confirmed that IGF2BP2 links with various carcinomas including breast, ovarian, colon, and glioma." (PMID 37308741, 2023). "Activation of the PI3K/Akt signaling pathway by IGF2BP2 (also known as Imp2, Insulin-like growth factor 2 mRNA-binding protein 2) promotes glioma progression, while its inhibition sensitizes glioma cells to temozolomide treatment." (PMID 37662954, 2023). "It has also been shown that SUMOylation of IGF2BP2 promotes angiogenic mimicry in gliomas by regulating the OIP5-AS1/miR-495-3p axis." (PMID 35989938, 2022). "Similar to our observations with circNEIL3, the panel of macrophage-derived immunosuppressive genes was dramatically upregulated in IGF2BP3 high expression gliomas compared with IGF2BP2 low expression gliomas in the TCGA dataset." (PMID 35031058, 2022). "In this study, western blot was found the high expression of IGF2BP2 in glioma tissues and cells, and IGF2BP2 expression level was positively correlated with pathological grade of glioma." (PMID 34345216, 2021). "For glioma, we found that IGF2BP2, KIAA1429, METTL16, METTL3, and YTHDF1 are consistently upregulated at the mRNA level of CGGA and GSE16011 datasets (7.97E-05 < FDR < 0.04)." (PMID 34589481, 2021). "Pearson correlation coefficient in glioma tissues identified a positive correlation between IGF2BP2 and DANCR expression." (PMID 35141227, 2021). "IGF2BP2 knockdown significantly reduced cell proliferation, migration, invasion and VM formation of glioma cells." (PMID 34345216, 2021). "To confirm IGF2BP2 expression in glioma, we used RT-qPCR to determine the mRNA expression of IGF2BP2 in human glioma tissues and normal brain tissues." (PMID 35141227, 2021). "For m6A readers, IGF2BP2 expression was reported to be enhanced, and promote proliferation, invasion, and migration of tumor in eight tumors including glioma." (PMID 34589481, 2021). "In summary, this study revealed for the first time that SUMOylation of IGF2BP2 promotes vasculogenic mimicry of glioma via regulating OIP5-AS1/miR-495-3p axis." (PMID 34345216, 2021). "In comparison with the IGF2BP2(-)+OIP5-AS1(+)NC group, in IGF2BP2(-)+OIP5-AS1(+) group, OIP5-AS1(+) reversed the inhibitory effect of IGF2BP2(-) on cell proliferation, migration, invasion, VM ability of glioma cells." (PMID 34345216, 2021).
glioma (continued). "In line with bioinformatics analysis, IGF2BP2 was observed to be upregulated in glioma tissue relative to normal brain tissues." (PMID 35141227, 2021). "The function of IGF2BP2 SUMOylation on glioma cells was further determined by using the subcutaneous and orthotopic transplantation model." (PMID 34345216, 2021). "The results of this study confirmed an important mechanism of IGF2BP2 SUMOylation in regulating VM of glioma." (PMID 34345216, 2021). "SUMOylation increased the expression and stability of IGF2BP2, and further promoted VM capacity of glioma cells via OIP5-AS1/miR-495-3p axis." (PMID 34345216, 2021). "The mutation of SUMOylation site significantly inhibited the SUMOylation of IGF2BP2, thereby reducing the VM capacity of glioma cells." (PMID 34345216, 2021). "Eventually, the tumor xenografts in nude mice further as certained the effects of IGF2BP2 SUMOylation on glioma cells." (PMID 34345216, 2021). "It has been shown that IGF2BP2 was a direct target of miR−188 in glioma, and IGF2BP2 under−expression served tumor−suppressive roles in glioma growth and metastasis." (PMID 32047515, 2019). "SUMOylation of IGF2BP2 is a crucial process in the control of VM in gliomas." (PMID 40919129, 2025). "OIP5–AS1, miR‐495‐3p, and IGF2BP2 could represent potential targets for glioma molecular targeted treatment." (PMID 40919129, 2025). "Among these, IGF2BP2 emerged as the most promising therapeutic target due to its role in maintaining tumor-initiating cell populations across multiple cancer types, including colon cancer and gliomas." (PMID 40347943, 2025). "However, IGF2BP2, an m6A reader, binds to let-7 miRNA, thereby sustaining glioma cells in an undifferentiated state and maintaining GSCs, thus promoting the progression of glioma." (PMID 40469294, 2025). "Additionally, within both TCGA‐LGG and TCGA‐GBM samples, higher grades of glioma correlated with a higher IGF2BP2 expression, suggesting its involvement in the malignant transformation of glioma cells." (PMID 38682020, 2024). "Furthermore, IGF2BP2, another m6A reader protein, has been shown to enhance chemoresistance in glioma cells." (PMID 39731162, 2024). "Further investigations are warranted to unravel the precise molecular mechanisms by which IGF2BP2 influences autophagy and to explore its potential as a therapeutic target in glioma treatment, as our study revealed that knockdown of IGF2BP2 can sensitize TMZ to advance the autophagy of cancer cells." (PMID 38682020, 2024). "These analyses highlighted IGF2BP2 as a potential prognostic marker for patients with glioma." (PMID 38682020, 2024). "Based on these findings, we proposed that knocking down IGF2BP2, which induces cell autophagy, could potentially enhance the sensitivity of glioma cells to TMZ." (PMID 38682020, 2024). "Several studies have revealed that IGF2BP2 plays a role in promoting glioma progression." (PMID 38682020, 2024). "In addition, miRNA-188 has been shown to inhibit human glioma progression by directly targeting IGF2BP2." (PMID 37964279, 2023). "In accordance with this, whether such regulation of Nrf2 by ALKBH5 and IGF2BP2 also has an influence on ferroptotic cell death in glioma needs to be further investigated." (PMID 37202791, 2023). "IGF2BP2 binds to let-7 miRNA recognition elements (MREs) and suppresses the silencing effect of let-7 on its target genes, thereby maintaining the stemness of GSCs and promoting glioma development." (PMID 38072944, 2023). "Furthermore, depletion of IGF2BP2 in glioma spheres decreases their oxygen consumption rate through compromising complex I and complex IV activity, which results in impaired clonogenicity in vitro and tumorigenicity in vivo." (PMID 35625706, 2022). "Similarly, the immunohistochemistry confirmed the upregulated expression of IGF2BP2 in glioma tissues." (PMID 35141227, 2021). "Western blot was used to detect the expression of IGF2BP2 in glioma tissues and cells." (PMID 34345216, 2021).
glioma (continued). "Collectively, these data indicated that IGF2BP2 was highly expressed in glioma." (PMID 35141227, 2021). "Among these genes, IGF2BP2 was significantly highly expressed in glioma." (PMID 35141227, 2021). "IGF2BP2 has been found to be upregulated in glioma and indicates a poor prognosis." (PMID 34645788, 2021). "Additionally, miR-188 is down-regulated in glioma cells and tissues, its over-expression inhibits proliferation, migration and invasion of glioma cells and tissues by directly targeting IGF2BP2." (PMID 33568150, 2021). "The results indicated that endogenous IGF2BP2 could bind to endogenous SUMO1 in glioma cells (U87 and U251) and undergo SUMOylation." (PMID 34345216, 2021). "In addition to IGF2BP1, inhibition of IGF2BP2 increases the sensitivity of glioma cells to TMZ." (PMID 40469294, 2025). "However, we did not observe that HMGA1 mRNA was significantly reduced after GSCAR knockdown in GSCs, suggesting that HMGA1 could be regulated either by IGF2BP2 or DHX9 in glioma tumor cells in different cellular contexts." (PMID 37063420, 2023). "Besides, colony formation assay and flow cytometry demonstrated that silencing IGF2BP2 potentiated the effect of etoposide to promote apoptosis and inhibit survival of glioma cells, whereas overexpression of DANCR exerted the opposite effect, abrogating the effect of sh-IGF2BP2 on glioma cells." (PMID 35141227, 2021). "SUMO increased IGF2BP2 expression and stability by blocking ubiquitination, and the OIP5–AS1/miR‐495‐3p axis further increased VM capacity in glioma cells." (PMID 40919129, 2025). "According to the molecular mechanism, HOTAIRM1 may improve PTBP1 and IGF2BP2's association, entice them to bind to SHMT2 mRNA, and then boost the quantity of SHMT2 protein by improving the stability of its mRNA, resulting in mitochondrial activity and the malignant growth of glioma." (PMID 40919129, 2025). "The Insulin-like Growth Factor 2 mRNA-Binding Proteins (IGF2BP) family, comprising IGF2BP1, IGF2BP2, and IGF2BP3, plays a crucial role in glioma development and response to treatment." (PMID 38474421, 2024). "IGF2BP2 promotes GSC clonogenicity by regulating oxidative phosphorylation (OXPHOS) and maintaining glioma cells’ oxygen consumption rates." (PMID 38072944, 2023). "Further, a recent study revealed that m6A methylation regulators, IGF2BP2 and IGF2BP3, in particular, play essential roles in the malignant progression of glioma." (PMID 36761737, 2023). "Subsequently, we discriminated all glioma samples into two groups of high and low HOXD‐AS2/IGF2BP2 expression in CGGA database, then GSEA and GSVA analysis were conducted to identify functional significance between groups." (PMID 37308741, 2023). "One recent study found that lncRNA HIF1A-AS2 interacted with IGF2BP2 and DHX9 to stabilize HMGA1 mRNA 46, and HMGA1 has been shown to promote glioma malignant progression by activting the PI3K/Akt/c-Jun signaling pathway." (PMID 37063420, 2023). "Silencing of specific key m6A regulators, such as IGF2BP2/3 in lung cancer and METTL3 in glioma, can reverse tumor radio-resistance via activation of DNA damage repair and inhibition of CSC functions." (PMID 35794625, 2022). "Based on the documented roles of DANCR and IGF2BP2 in glioma and their correlation in certain cancers, we aimed in this study to explore the interaction between DANCR and IGF2BP2 in drug resistance in GBM cells." (PMID 35141227, 2021). "Collectively, IGF2BP2 inhibits PID1 expression through the DANCR/FOXO1 axis, inducing drug resistance in GBM cells, and promoting glioma progression." (PMID 35141227, 2021). "To identify the potential relationship between IGF2BP2 and DANCR in glioma, we conducted a correlation analysis through GEPIA, which indicated a significant correlation between them, whereas DANCR was also identified to be highly expressed in glioma." (PMID 35141227, 2021).
glioma (continued). "Knockdown of IGF2 mRNA-binding protein 2 (IGF2BP2) is noted to decrease the expression of long noncoding RNAs (lncRNAs) and tight junction–related proteins, thereby promoting BTB permeability in glioma and enhancing antitumor efficacy of certain drugs." (PMID 35141227, 2021). "Our results suggested that IGF2BP2, KIAA1429, METTL16, and METTL3, as well as 208 targets are involved in the occurrence of glioma, GBM, and LGG." (PMID 34589481, 2021). "Taken together, these results indicated that IGF2BP2, KIAA1429, METTL16, and METTL3, as well as 208 targets are involved in the occurrence of glioma, GBM, and LGG." (PMID 34589481, 2021). "Knockdown of IGF2BP2 and knockdown or overexpression of OIP5-AS1 plasmid co-transfection in U87 and U251 cells to further detect their functions in glioma." (PMID 34345216, 2021). "We found that the expression of IGF2BP2 and OIP5-AS1 were up-regulated in glioma tissues and cells, while miR-495-3p was down-regulated." (PMID 34345216, 2021). "RT-PCR and western blot were used to detect the expression levels of IGF2BP2, OIP5-AS1, and miR-495-3p in glioma tissues and cell lines." (PMID 34345216, 2021). "IGF2BP2 (also known as Imp2) activates the PI3K/Akt signaling pathway and thereby promotes glioma progression, whereas its inhibition sensitizes glioma cells to temozolomide treatment." (PMID 35141227, 2021). "IGF2BP2 and DANCR were highly expressed in glioma cells and tissues, whereas PID1 and FOXO1 were poorly expressed." (PMID 35141227, 2021). "CCK-8 assays, cell transwell assays, and three-dimensional cell culture methods were used for evaluating the function of IGF2BP2, OIP5-AS1, miR-495-3p, HIF1A and MMP14 in biological behaviors of glioma cells." (PMID 34345216, 2021). "Knockdown of IGF2BP2 and OIP5-AS1 significantly inhibited cell proliferation, migration, invasion and VM formation of glioma cells." (PMID 34345216, 2021). "The expressions of IGF2BP2 and OIP5-AS1 were up-regulated and the expression of miR-495-3p was down-regulated in both glioma tissues and cells." (PMID 34345216, 2021). "Treatment for gliomas requires further research, and the molecular targets miR‐495‐3p, OIP5–AS1, and IGF2BP2 could become apparent in the future." (PMID 40919129, 2025). "Additionally, IGF2BP2 stabilizes transcripts like NUP214 and FLOT1, influencing glioma progression and TMZ resistance." (PMID 38474421, 2024). "Both IGF2BP2 and IGF2BP3 are overexpressed in high-grade gliomas and indicate poor prognosis." (PMID 38072944, 2023). "Previous results revealed that IGF2BP2 bound with HOXD‐AS2 and affected its expression, implying that whether HOXD‐AS2/IGF2BP2 genes' highly expression aggravated glioma progression." (PMID 37308741, 2023). "Collectively, m6A RNA methylation regulators KIAA1429, METTL16, METTL3, IGF2BP2, and YTHDF, and targets NASP, TIMP1, U2AF2, COL18A1, and VEGFA could serve as oncogenes in glioma, while PHLPP2 is a tumor suppressor." (PMID 34589481, 2021). "In conclusion, m6A RNA methylation regulators KIAA1429, METTL16, METTL3, IGF2BP2, and YTHDF1, as well as their targets may play a critical role in the occurrence of glioma, which may be beneficial to therapeutic customization and clinical decision-making." (PMID 34589481, 2021). "IGF2BP2, OIP5-AS1 and miR-495-3p may become new targets for molecular targeted therapy of glioma, and the research on the treatment of gliomas needs to be further studied." (PMID 34345216, 2021). "IGF2BP2 enhances the stability of OIP5-AS1, thereby increasing the binding of OIP5-AS1 to miR-495-3p, weakening the binding of miR-495-3p to the 3'UTR of HIF1A and MMP14 mRNA, and ultimately promoting the formation of VM in glioma." (PMID 34345216, 2021). "We further detected the endogenous expression levels of IGF2BP2, OIP5-AS1, and miR-495-3p in both glioma tissues and cells, and further explored the mutual regulatory mechanism between these molecules and their effects on VM capacity of glioma cells." (PMID 34345216, 2021).
glioma (continued). "At present, the study of IGF2BP2 on VM of glioma has not been reported." (PMID 34345216, 2021).